PIK3CA (phosphatidylinositol-4,5-bisphosphate 3-kinase catalytic subunit alpha)
Diseases named in the same sentence as PIK3CA in open-access papers (continued):
Sharing a sentence is not in itself a finding about the gene and the disease.
breast cancer (continued). "Capivasertib showed pre-clinical efficacy when used as a single agent for treating human breast cancer cell lines with alterations in PIK3CA and MTOR, and more so when combined with anti-HER2 and endocrine therapy." (PMID 39614261, 2024). "Treatment with alpelisib–fulvestrant has been found to prolong PFS among patients with PIK3CA-mutated, HR-positive, HER2-negative, advanced breast cancer who had received endocrine therapy previously in the SOLAR-1 phase III clinical trial." (PMID 38869741, 2024). "The association between PIK3CA mutations and TNBC subtypes is a pivotal aspect of molecular characterization, shedding light on the intricate heterogeneity within this aggressive breast cancer category [15,]." (PMID 39369580, 2024). "In fact, PIK3CA/AKT is the most frequent tumor somatic alteration in breast cancer, occurring in >30% of invasive tumors." (PMID 38256137, 2024). "Another study investigated RNA interference (RNAi) targeting the PIK3CA oncogene in breast cancer cells." (PMID 38794316, 2024). "Common mutations included EGFR (29%), in 86 lung cancer patients, and PIK3CA (22%), identified in 13 breast cancer patients." (PMID 39061145, 2024). "Alpelisib, the pioneering PI3Kα inhibitor used for breast cancer treatment, has extended progression-free survival in patients with HR+/HER2- metastatic breast cancer carrying PIK3CA mutations when combined with Fulvestrant (NCT02437318)." (PMID 39290699, 2024). "This detection method offers a promising avenue for on-site and real-time sensitive detection of the PIK3CA-H1047R antigen, potentially revolutionizing breast cancer diagnosis." (PMID 39070168, 2024). "PIK3CA is an oncogene involved in several cancers, including breast cancer, gastric cancer, and CRC." (PMID 38785271, 2024). "A novel small molecule PI3K inhibitor, inavolisib, has more than doubled progression-free survival when combined with CDK4/6 inhibitor palbociclib plus fulvestrant in patients with recurrent PIK3CA-mutated, HR–positive, HER2-negative advanced breast cancer." (PMID 38542380, 2024). "Our meta-analysis results suggested the PIK3CA gene as a predictor for pCR in TA-treated breast cancer patients with PIK3CA mt (17.1%) and PIK3CAwt (24.7%)." (PMID 38576013, 2024). "The combination of Ipatasertib with lapatinib has successfully overcome resistance to HER2 treatment in vitro in PIK3CA-mutant HER2+ breast cancer cells." (PMID 39769140, 2024). "The FAKTION trial is a phase II study investigating the efficacy of Capivasertib in combination with fulvestrant for patients with ER+ and PIK3CA-mutant breast cancer." (PMID 39769140, 2024). "Comprehensive KEGG pathway analysis of the DEGs revealed that the ROCK1 and PIK3CA signalling pathways were closely related to the occurrence and development of breast cancer." (PMID 39054484, 2024). "The IPATHER study is a phase Ib trial designed to evaluate the safety and efficacy of Ipatasertib in combination with trastuzumab and pertuzumab in patients with locally advanced/unresectable or metastatic PIK3CA-mutant HER2+ breast cancer." (PMID 39769140, 2024). "We also tested the effect of onvansertib in combination with inavolisib, a selective inhibitor and degrader of mutant PI3Kα that is currently under clinical evaluation for PIK3CA-mutant breast cancer." (PMID 39409880, 2024). "Mutations in PIK3CA p.E545K and amplification in ERBB2 were common in breast cancers, BRAF p.V600E in metastatic melanoma and IDH1 p.R132H in IDH-mutant gliomas." (PMID 39289779, 2024). "The panel was applied to samples from HR+ breast cancer cell lines with known activating PIK3CA or AKT1 alterations published in COSMIC (RRID:SCR_002260)." (PMID 38954770, 2024).
breast cancer (continued). "Our analysis revealed that 40.9% of patients were positive for the PIK3CA mutation, which is consistent with the findings of previous studies indicating a high prevalence of these mutations in HR+/HER2− advanced breast cancer." (PMID 39742376, 2024). "For instance, the phase 2 TIFA trial compare a ketogenic diet (<50g carbohydrate daily), a low carbohydrate diet (<100g carbohydrate daily), and SGLT2i for the treatment of hyperglycemia in patients with metastatic PIK3CA-mutant breast cancer on alpelisib." (PMID 39437820, 2024). "The findings support further investigation of this regimen for PIK3CA-mutant HR+ breast cancer patients who show resistance to ET and CDK4/6i or cross-resistance to PI3Kα inhibitors." (PMID 39409880, 2024). "Although targeted therapy is already becoming the optimal treatment for the early breast cancer, PIK3CA inhibitors remain the gold standard for treating metastatic disease." (PMID 39742376, 2024). "Through a comprehensive analysis encompassing multiple genomic changes within the PI3K pathway, including not only PIK3R1 mutations but also mutations in PIK3CA and PTEN, a more nuanced understanding of the molecular landscape of breast cancer emerges." (PMID 38172946, 2024). "AREG has been previously and independently established as a signaling molecule required for the growth of PIK3CA-mutant breast cancer cells." (PMID 38802751, 2024). "RhoC overexpression also enhanced mammary tumor formation in an activated Pik3ca model for breast cancer (Pik3caH1047R)." (PMID 38807216, 2024). "Despite the challenges that remain, the rapid evolution of PIK3CA-targeted therapies, including combination approaches and the exploration of novel targets, offers significant promise in revolutionizing the treatment of breast cancers with PIK3CA alterations." (PMID 39369580, 2024). "Clinically, this principle has proven effective, as seen in the case of PIK3CA-AKT pathway vulnerability in CDK4/6 inhibitor-treated hormone receptor (HR) + breast cancer." (PMID 39501277, 2024). "Using machine learning algorithms on multi-omics data from over 6,000 breast cancer patients, we identified six key genes significantly associated with VM and patient risk scores: EP300, PIK3CA, DMXL1, LS, ABL2, and CDK4." (PMID 39165361, 2024). "Activating mutations in PIK3CA, the gene encoding the p110α catalytic domain of PI3K, is one of the frequently altered genes in HR+ breast cancer (~40%) and is implicated in resistance to therapy." (PMID 39409880, 2024). "This study aimed to evaluate the efficacy of combining alpelisib with a highly specific PLK1 inhibitor, onvansertib, in PIK3CA-mutant HR+ breast cancer preclinical models." (PMID 39409880, 2024). "Mutations in the phosphatidylinositol-4,5-bisphosphate 3-kinase catalytic subunit alpha (PIK3CA) gene are present in approximately 40% of patients with HR+/HER2- breast cancer and are correlated with poor prognosis in advanced stages of the disease." (PMID 39555080, 2024). "We found that compared to cells with wild-type PIK3CA (n = 13), PIK3CA-mutant breast cancer cell lines (n = 7) displayed increased dependency on PDK1 and were more susceptible to PDK1 knock-out for their proliferative capacity." (PMID 38273040, 2024). "The combination of CDK4/6‐PI3K inhibition in PIK3CA mutant breast cancer PDXs has also shown promise." (PMID 39329017, 2024).
breast cancer (continued). "Mutations in PIK3CA, which encodes PI3K, have been observed in about 40% of patients with HR+ breast cancer." (PMID 38339303, 2024). "In breast cancer, miR-19a-3p has been identified as a key regulator of PIK3CA, a central component of the PI3K/AKT pathway, which is known to promote tumor growth and survival." (PMID 39850811, 2024). "Our preclinical studies demonstrate the synergistic efficacy of the PI3Kα inhibitor alpelisib and the PLK1 inhibitor onvansertib in PIK3CA-mutant HR+ breast cancer cell lines and PDXs that are resistant to ET and palbociclib." (PMID 39409880, 2024). "In patients with HER2 therapy-resistant breast cancer, increased HER3 expression by trastuzumab and PIK3CA mutation or PTEN loss can lead to PI3K activation." (PMID 38396649, 2024). "Our findings demonstrated that onvansertib synergizes with alpelisib in PIK3CA-mutant HR+ breast cancer cell lines and patient-derived xenografts that are resistant to ET and cyclin-dependent kinase 4/6 inhibitors." (PMID 39409880, 2024). "The PIK3CA gene was found to have higher correlation in microarray for renal cancer and breast cancer, while other genes showed better results in RNA-seq." (PMID 38463169, 2024). "Ribociclib exhibited higher IC50 values in DLD-1 (PIK3CA/KRAS-mutated) and Caco-2 (PIK3CA/KRAS wild-type) lines (IC50 >15 μM) compared to breast cancer models, though values for the SNUC4 (PIK3CA-mutated) and LS1034 (KRAS-mutated) lines were comparable." (PMID 39769028, 2024). "Dysregulation of the PI3K/AKT/mTOR pathway by activating mutations in PIK3CA and AKT1 and/or inactivating PTEN are most frequently observed in HR+/HER2- BCs, which are found to be mutually exclusive (GENIE breast cancer cohort)." (PMID 39796647, 2024). "In breast cancer, PI3K/AKT/mTOR is frequently activated due to mutations in genes like PIK3CA and the amplification of receptor tyrosine kinases like HER2." (PMID 39770406, 2024). "However, the rate of mutations may increase in advanced TNBC, reflecting the high rate of observed PIK3CA mutations in initially ER+ breast cancer, which relapses, loses ER expression and becomes secondary TNBC while retaining the high rate of activating PI3Ks." (PMID 39369580, 2024). "The BAX gene was recurrently found in colorectal cancer, renal cancer, and ovarian cancer, and the PIK3CA gene belonged to renal cancer and breast cancer." (PMID 38463169, 2024). "Proteins that differed between the patient groups were subsequently quantified in AKT1- or PIK3CA-altered breast cancer cell lines with varying capivasertib sensitivity." (PMID 38954770, 2024). "Research on PIK3CA resistance has mainly concentrated on breast cancer cells, with limited focus on understanding resistance mechanisms in NSCLC." (PMID 38655260, 2024). "We concluded that GluOC promotes the proliferation and apoptosis of MDA-MB-231 breast cancer cells through the ROCK1/JAK2/PIK3CA signalling pathway." (PMID 39054484, 2024). "Capivasertib is approved for use in combination with fulvestrant for patients with advanced breast cancer whose tumors have one or more PIK3CA/AKT1/ PTEN alterations." (PMID 39510293, 2024). "PIK3CA, the gene encoding the p110α catalytic subunit of PI3K, was found to be frequently mutated in breast cancer (27%)." (PMID 39369580, 2024). "The combination of ADCs with PIK3Ca inhibitors is an area of research interest in breast cancer treatment." (PMID 39093344, 2024).
breast cancer (continued). "The top five genes (NAT1, PPM1H, AREG, ACSS1, CXCL1) with the greatest differences in Z-scores were evaluated in the PIK3CA mutant breast cancer samples from TCGA." (PMID 38802751, 2024). "Using patient data from The Cancer Genome Atlas (TCGA) Breast Cancer (BRCA) data set, RNA-seq samples from tumors bearing each PIK3CA mutation confirmed observations made within our isogenic MCF-10A panel." (PMID 38802751, 2024). "It is noteworthy that the majority of studies investigating PIK3CA resistance have primarily focused on breast cancer cells, while there remains a paucity of research specifically examining resistance mechanisms in NSCLC." (PMID 38655260, 2024). "A trial (Capello-291, NCT04305496) assessed the efficacy of capivasertib in combination with fulvestrant in patients with inoperable or metastatic HR-positive and HER2-negative breast cancer, including those with PIK3CA/AKT1/PTEN alterations." (PMID 38791529, 2024). "Compare contrasts two attribute values of the same type (e.g. mutations and copy number alterations) in the context of other attribute types (e.g. PIK3CA and breast cancer)." (PMID 38182884, 2024). "Recently, the FDA approved the use of inavolisib with palbociclib and fulvestrant for endocrine-resistant, PIK3CA-mutated HR+ and HER2- advanced breast cancer." (PMID 39769140, 2024). "For example, the United States Food and Drug Administration (FDA)-approved drugs (Level 1) are available for alterations in ERBB2, PIK3CA for breast cancer and other biomarkers such as MSI-High, TMB-High for all solid tumors." (PMID 39706915, 2024). "As a result, genome alterations such as PIK3CA mutation and the loss of PTEN expression, which upregulates the PI3K pathway, can also promote estrogen-independent ER activation and render breast cancer cells resistant to endocrine therapy." (PMID 39796647, 2024). "What is the association of PIK3CA mutations, response to therapy, and outcome by hormone receptor (HR) status and intrinsic subtype among patients with ERBB2/HER2-positive early breast cancer (EBC) treated in a clinical trial?" (PMID 38117494, 2023). "Alpelisib was recently approved for advanced PIK3CA-mutant ER+ breast cancer in combination with fulvestrant, which prolongs relapse-free survival but does not prevent disease recurrence." (PMID 37471270, 2023). "The co-mutation of CDH1 with PIK3CA and ERBB2 contributes to endocrine resistance in breast cancer patients with invasive lobular carcinoma." (PMID 37426414, 2023). "A connection between the CDK/Rb and PI3K pathway was discovered when it was shown that CDK 4/6 inhibitors sensitize PIK3CA mutant breast cancer to PI3K inhibitors." (PMID 37877351, 2023). "Our study included 2609 primary breast cancer samples from the TCGA and METABRIC datasets that were classified based on tumor subtype and the existence of mutations in PIK3CA and ARID1A genes." (PMID 38017109, 2023).
breast cancer (continued). "PIK3CA mutations are commonly found in hormone receptor-positive and HER2-negative breast cancer, with 57.1% of patients with hormone receptor-positive breast cancer in this study having PIK3CA mutations." (PMID 37747019, 2023). "Alpelisib, a PI3K inhibitor, is approved for patients with HR+, HER2- and PIK3CA-mutated cancers in combination with fulvestrant, while the PARP inhibitor olaparib targets BRCA mutations in early breast cancer." (PMID 37513912, 2023). "Other oncogenes that can raise tRNA expression include MDM2, CCND and PIK3CA, all of which are sometimes amplified in breast cancers." (PMID 37509247, 2023). "In this study, we evaluated the efficacy of alpelisib in HER2+/PIK3CA mutant breast cancer using in vitro and in vivo models." (PMID 37469415, 2023). "Although other mutations are rarely detected in PIK3CA, a study reported the A3140G mutation in approximately 29% (18/62) of CMT specimens, which was higher than that observed in human breast cancer samples (14.3%)." (PMID 38033642, 2023). "We also developed HER2+/PIK3CA mutant breast cancer models of acquired resistance to alpelisib to investigate the molecular mechanisms underlying resistance." (PMID 37469415, 2023). "The PI3K/AKT/mTOR pathway is frequently activated in breast cancer brain metastases due to PTEN loss of function and frequent PIK3CA, AKT and mTOR activating mutation, as evidenced in our meta-analysis." (PMID 36980614, 2023). "In this trial, capivasertib showed a reduction in tumor size in PIK3CA-mutant breast cancer patients." (PMID 37415164, 2023). "Many studies have analyzed the specific mutations in various genes, such as BRCA1, BRCA2, and phosphatidylinositol-4,5-bisphosphate 3-kinase catalytic subunit alpha (PIK3CA), using human breast cancer cell lines." (PMID 38033642, 2023). "Several independent groups have undertaken RNA profile analysis of primary human breast cancers and mouse models of PIK3CA mutant ER+ breast cancer and uncovered AKT-independent downstream signaling events that contribute to tumor progression." (PMID 37471270, 2023). "In this paper, we explore the clinical landscape of 100 PIK3CA-positive breast cancer patients, as identified by next-generation sequencing." (PMID 37761256, 2023). "The entire protein-coding regions of PIK3CA were sequenced using WES in each of the 45-breast cancer tissue as well as corresponding blood sample." (PMID 37821962, 2023). "Two of them, PIK3CA H1047L and ERBB2 V777L, are well-known mutations, which often occur in breast cancers and lead to the activation of the respective protein." (PMID 36823365, 2023). "The PI3Kα inhibitor, alpelisib, was initially found to up-regulate ER-dependent transcriptional activity in PIK3CA-mutant ER+ breast cancer xenografts, which was circumvented by co-treatment with the selective estrogen receptor degrader (SERD), fulvestrant." (PMID 37471270, 2023). "In HR− breast cancer, HER2-zero breast cancer harbored fewer PIK3CA mutations than HER2-positive and HER2-low breast cancer in the TCGA database." (PMID 37264417, 2023).